LGI1 (leucine rich glioma inactivated 1)
Diseases named in the same sentence as LGI1 in open-access papers (continued):
Sharing a sentence is not in itself a finding about the gene and the disease.
encephalitis (continued). "In this study, we determined the clinical manifestations of patients newly diagnosed with anti-LGI1 encephalitis, and, for the first time, analyzed their gut microbiota." (PMID 33193049, 2020). "Anti-LGI1 Ab, anti-GABABR, and anti-AMPAR Ab-associated encephalitis mainly involve the limbic system and are called autoimmune LE." (PMID 33162923, 2020). "The most commonly brain alteration in anti-LGI1 encephalitis was hippocampal atrophy in the previous MRI studies." (PMID 32317923, 2020). "The clinical phenotype of anti -LGI1 encephalitis is usually manifested as cognitive impairment, seizures, faciobrachial dystonic seizures (FBDS), and hyponatremia." (PMID 33551968, 2020). "Taken together, DIRS demonstrated high sensitivity in detecting an intrathecal B-cell response and marked interconnectivity between the PB and CSF compartments in LGI1 antibody encephalitis, particularly of the more mature B-cell subsets." (PMID 32029531, 2020). "One case of anti LGI1 encephalitis complicated with FDBs showed hyperintense T1 signal in basal ganglia on MRI, while hypermetabolism was found in the same area on PET." (PMID 33380947, 2020). "This further advocates the mitigating role of rituximab in anti‐LGI1 encephalitis, especially in the relapsing cases, both in terms of improving mRS score and maintaining long‐term disease remission." (PMID 32783406, 2020). "Patients with LGI1-Ab encephalitis had markedly decreased TST (p = 0.018) and sleep efficiency (p = 0.040)." (PMID 32849186, 2020). "In clinical practice, anti-LGI1 encephalitis has often been misdiagnosed as psychiatric illness or viral encephalitis, which can delay immunotherapy and cause the deterioration of symptoms." (PMID 33510707, 2020). "Disruptions of large-scale functional networks including default mode network (DMN), sensorimotor, salience and higher visual networks in patients with anti-LGI1 encephalitis have been revealed in the resting-state fMRI study." (PMID 32317923, 2020). "Paired CSF and peripheral blood (PB) mononuclear cells were collected from 6 patients with LGI1 antibody encephalitis and 2 patients with other neurologic diseases." (PMID 32029531, 2020). "Although most patients with anti-LGI1 encephalitis respond well to immunotherapy, a small number of patients still have cognitive disorders, mainly recent memory impairment, after 1 year." (PMID 33162923, 2020). "The recognition of this characteristic clinical phenotype is important because FBDS are highly specific for LGI1-encephalitis and typically occur early and often before onset of limbic encephalitis." (PMID 33324912, 2020). "Anti-leucine-rich glioma-inactivated 1 (anti-LGI1) encephalitis is a rare autoimmune encephalitis (AE)." (PMID 33193049, 2020). "In anti‐LGI1 encephalitis, medial temporal hypermetabolism indicated a more severe condition, whereas the absence of medial temporal hypermetabolism was related to good outcome." (PMID 31985135, 2020). "This study aimed to explore clinical characteristics of cognitive impairment and 1-year outcome in patients with anti-LGI1 encephalitis." (PMID 33162923, 2020). "And we also compared our heavy chain common clone with the data of patients with anti-LGI1 encephalitis or NMOSD." (PMID 32849520, 2020). "Fifteen patients newly diagnosed with anti-LGI1 encephalitis before immunotherapy and 25 age-, gender-, and BMI-matched HCs were recruited." (PMID 33193049, 2020). "The lesion overlap map showed that, in addition to classic limbic system involvement, BG was another important target for anti-LGI1 encephalitis." (PMID 33510707, 2020). "Regional locations and significant comparisons of the independent component maps between patients with anti-LGI1 encephalitis and normal controls." (PMID 32317923, 2020). "The imaging manifestations of anti-LGI1 encephalitis patients mainly were high T2 signal and fluid-attenuated inversion recovery (FLAIR) in the bilateral temporal lobe." (PMID 33162923, 2020).
encephalitis (continued). "These network changes indicate cognitive deficits beyond mere memory impairment in LGI1 encephalitis, suggesting brain-wide alteration of the connectome triggered by focal hippocampal damage." (PMID 32873782, 2020). "Meanwhile, TBSS analysis revealed widespread structural white matter damage in anti-LGI1 encephalitis as assessed using DTI." (PMID 32317923, 2020). "In this study, we found that patients with LGI1 antibodies encephalitis presented reduced functional connectivities in the hippocampus, IFG, STG, ACC, PCC and amygdala, while increased functional connectivities in putamen, caudate and SMA." (PMID 32317923, 2020). "Although meso-temporal sclerosis has been described in 25-50% of follow-up MRIs in patients with anti-LGI1 encephalitis, only a few develop epilepsy after resolved encephalitis." (PMID 32827010, 2020). "Although both are AE subtypes, the triggers for anti-LGI1 encephalitis and anti-NMDAR encephalitis are likely to be distinct." (PMID 33193049, 2020). "Among the cases we studied, one case was diagnosed as anti-LGI1 encephalitis at the time of 9 months after the onset of the disease, and the effect of immunotherapy was poor." (PMID 33162923, 2020). "In conclusion, sleep disorders in LGI1-encephalitis patients included insomnia, hypersomnia, RBD, PLMS, and OSAS." (PMID 32849186, 2020). "The Simpson index was higher, while the other indices were lower in patients with anti-LGI1 encephalitis compared to the HCs group." (PMID 33193049, 2020). "PSGs in patients with LGI1-Ab encephalitis demonstrated a decrease in TST, sleep efficiency, and the percentages of REM and N3 sleep stages but a marked increase in LMS index." (PMID 32849186, 2020). "Although most patients of anti-LGI1 encephalitis had a good cognitive outcome, a small number of patients still have cognitive impairment, mainly short-term memory loss after 1 year." (PMID 33162923, 2020). "The Venn figure depicted that 376 and 727 OTUs were unique to the anti-LGI1 encephalitis patients and HCs, respectively." (PMID 33193049, 2020). "Subsequently, anti-LGI1 encephalitis, a form of limbic encephalitis was confirmed as an autoimmune encephalitis panel revealed anti-LGI1 antibody positive result in serum." (PMID 32827010, 2020). "We compared the data of patients with anti-NMDAR encephalitis, anti-leucine-rich glioma inactivated 1 (anti-LGI1) encephalitis, multiple sclerosis (MS), neuromyelitis optica spectrum disorder (NMOSD), and public healthy controls." (PMID 32849520, 2020). "The common sequela of anti-LGI1 encephalitis is cognitive impairment, especially recent memory impairment." (PMID 33162923, 2020). "Anti-LGI1 encephalitis presented with subacute or acute onset of cognitive impairment, psychiatric disturbances, faciobrachial dystonic seizures (FBDSs), convulsions, and hyponatremia." (PMID 33162923, 2020). "One patient was diagnosed with anti-LGI1 encephalitis 9 months after the onset of the disease, and brain MRI showed hippocampal atrophy." (PMID 33162923, 2020). "Involvement was also seen in the frontal and temporal lobes, suggesting anti‐LGI1 encephalitis attacks multiple areas of the brain beyond the limbic system." (PMID 32783406, 2020). "In anti-LGI1 encephalitis there was a higher frequency of hypersignal on MRI, which is questionable, considering the small sample." (PMID 33551968, 2020). "The within-sample diversity of fecal microbiota was lower in anti-LGI1 encephalitis patients compared with HCs." (PMID 33193049, 2020). "In a study of 18 anti-LGI1 encephalitis patients with seizures, abnormalities were found in 50% of patients and most commonly involved the middle temporal lobe." (PMID 33380947, 2020). "Anti-LGI1 encephalitis is the second most common type of autoimmune encephalitis known, which can lead to memory impairment and various forms of seizures, among which faciobrachial dystonic seizure (FBDS) was representative to a certain extent." (PMID 33380947, 2020).
encephalitis (continued). "Prior neuroimaging studies have reported structural and functional neural differences in various brain areas between anti-LGI1 encephalitis patients and normal controls (NC)." (PMID 32317923, 2020). "Our results suggest that anti-LGI1 encephalitis is characterized by special clinical features and is accompanied by alterations in specific gut microbiota." (PMID 33193049, 2020). "Encephalitis with leucine-rich, glioma-inactivated 1 (LGI1) antibodies is a disease characterized by progressive memory loss, confusion, sleep disturbances, and problems with behaviors and spatial orientation." (PMID 32317923, 2020). "Fifteen patients newly diagnosed with anti-LGI1 encephalitis were recruited in the study prior to the administration of immunotherapy." (PMID 33193049, 2020). "The anti-LGI1 encephalitis patients exhibited increased connectivity in motor-related brain areas including putamen, caudate and SMA." (PMID 32317923, 2020). "The specific bacterial genera differentially distributed between anti-LGI1 encephalitis and HCs were also identified." (PMID 33193049, 2020). "Correspondingly, MR imaging in the acute phase of LGI1 or CASPR2 encephalitis is usually abnormal, typically showing inflammation in MTL, an area critically involved in memory processing." (PMID 32873782, 2020). "The aim of this study is to characterize the clinical presentation and 1-year outcome, especially cognitive impairment in patients with anti-LGI1 encephalitis." (PMID 33162923, 2020). "Our findings illustrate specific clinical features of anti-LGI1 encephalitis and provided preliminary evidences of gut dysbiosis." (PMID 33193049, 2020). "Evidence of SD in patients with LGI1-Ab encephalitis showed that these patients are more likely to have simple limb movements." (PMID 32849186, 2020). "The hippocampal atrophy and impaired hippocampal microstructural integrity have been reported in encephalitis with LGI1 antibodies in the previous studies." (PMID 32317923, 2020). "Most patients with NSAb-associated AE have seizures, particularly LGI1 AE, anti-NMDAR encephalitis, and anti-GABABR encephalitis." (PMID 32431657, 2020). "In the PCoA based on weighted UniFrac distance, a significant difference in the overall composition of microbial community was observed between the patients with anti-LGI1 encephalitis and HCs (pseudo-F: n, p < 0.001)." (PMID 33193049, 2020). "Sphingomonas, Anaerofustis, Succinivibrio, Clostridium, and SMB53 genera were remarkly outnumbered in the patients with anti-LGI1 encephalitis." (PMID 33193049, 2020). "Compared to HCs, the anti-LGI1 encephalitis patients exhibited a decreased microbial diversity and an altered overall composition of gut microbiome." (PMID 33193049, 2020). "As the most common type of VGKC-Ab encephalitis, cognitive disorders are common in anti-LGI1 encephalitis." (PMID 33162923, 2020). "In accordance with reported results from healthy human guts, fecal microbiota from anti-LGI1 encephalitis patients and HCs in this study predominantly belong to the Bacteroidetes and Firmicutes phyla." (PMID 33193049, 2020). "Fluorodeoxyglucose (FDG)-positron emission tomography (PET) is more sensitive than EEG and MRI in detecting abnormalities in LE, particularly in LGI1 and contactin-associated protein-like 2 (CASPR2) encephalitis." (PMID 33396564, 2020). "The microstructural integrity impairments of the hippocampus, corona radiata, capsula interna and corpus callosum were found in patients with anti-LGI1 encephalitis in the DTI studies." (PMID 32317923, 2020). "The common manifestations of anti-LGI1 encephalitis are cognitive impairment or rapidly progressive dementia, psychiatric disturbances, convulsions, faciobrachial dystonic seizures (FBDSs), and refractory hyponatremia." (PMID 33162923, 2020). "Here, we described a Chinese woman with frequent pilomotor seizures who was finally diagnosed as having anti-LGI1 encephalitis." (PMID 32153488, 2020).
encephalitis (continued). "Sleep disorders are prominent manifestations of Morvan's syndrome and also commonly seen in LGI1-Ab encephalitis." (PMID 32849186, 2020). "In conclusion, the present study reviewed brain MRI results of patients with anti-LGI1 encephalitis and identified several characteristic radiological patterns." (PMID 33510707, 2020). "MRI abnormalities in MTL at the early stage of the disease are an important basis for the diagnosis of anti-LGI1 encephalitis." (PMID 33380947, 2020). "Patients with anti-LGI1 encephalitis exhibited subacute cognitive impairment, FBDS, hyponatremia, and psychiatric symptoms as its core clinical characteristics, while abnormal EEG or brain MRI were detected in some." (PMID 33193049, 2020). "With the reported incidence of 0.83/million/year (in Netherlands in 2015), anti-LGI1 encephalitis most frequently occurs in the elderly with a male predominance." (PMID 33193049, 2020). "In this study, we investigated the clinical manifestations and analyzed the gut microbiota in newly diagnosed anti-LGI1 encephalitis patients." (PMID 33193049, 2020). "BCR data of healthy persons, and of patients with anti-leucine-rich glioma inactivated 1 (anti-LGI1) encephalitis, multiple sclerosis (MS), and neuromyelitis optica spectrum disorder (NMOSD) from the public databases were used as control." (PMID 32849520, 2020). "This has been the consistent observations in such cases of anti LGI1 antibody-related encephalitis by other studies and authors." (PMID 32827010, 2020). "For the limited sample size and non-applicability to other populations, further studies are warranted to explore the relationships between gut microbiota and anti-LGI1 encephalitis." (PMID 33193049, 2020). "At present, most patients with anti-LGI1 encephalitis have a relatively good prognosis after immunotherapy." (PMID 33162923, 2020). "The common sequela of anti-LGI1 encephalitis is cognitive disorder, but there are few studies on the recovery of cognitive function after immunotherapy." (PMID 33162923, 2020). "The most commonly described variant was anti‐LGI1 encephalitis (13 studies, 139 patients), followed by anti‐GABABR (9 studies, 114 patients), and anti‐CASPR2 encephalitis (3 studies, 10 patients)." (PMID 32783406, 2020). "Brain MRI in most patients with anti-LGI1 encephalitis shows a hyperintense signal in the unilateral or bilateral medial temporal lobes." (PMID 33162923, 2020). "The results preliminarily identified the specificity of anti-LGI1 encephalitis in clinical features and intestinal flora." (PMID 33193049, 2020). "Fifteen of 19 anti-LGI1 encephalitis patients were treated with chronic immunotherapy MMF 750 mg twice daily." (PMID 33162923, 2020). "Faciobrachial dystonic seizures are very specific for LGI1-encephalitis, but only present in about 50% of patients." (PMID 33396564, 2020). "As the first detection of gut microbiome in patients with anti-LGI1 encephalitis, this study shows a specific microbiota landscape in the patient group that is distinct from HCs." (PMID 33193049, 2020). "Further studies with an expanded samples size will be done to evaluate the relationships between gut microbiota, and different clinical characteristics or different disease phases of anti-LGI1 encephalitis." (PMID 33193049, 2020). "We identified status dissociatus (SD) in five (23.8%) patients with LGI1-Ab encephalitis and two (40%) patients with Caspr2-Ab diseases." (PMID 32849186, 2020). "Continuous insomnia was more common in patients with Caspr2-Ab diseases than patients with LGI1-Ab encephalitis." (PMID 32849186, 2020). "The motor cortex has been demonstrated as one of the major signs of LGI1-antibody encephalitis with striatum involvement in parallel." (PMID 32317923, 2020). "In this study, we demonstrated that MRI plays a significant role in the diagnosis of anti-LGI1 encephalitis, whose main features are MTL or BG hyperintensities on T2WI/FLAIR." (PMID 32581996, 2020).
encephalitis (continued). "We identified nine clusters of ICs that were significantly reliable and reproducible in their spatial patterns across anti-LGI1 encephalitis patients and normal controls groups by HPM-ICA method." (PMID 32317923, 2020). "Based on previous studies, various HLA-A and HLA-DRB1 alleles have been shown to be associated with increased susceptibility to multiple autoimmune diseases, such as anti-LGI1 encephalitis, multiple sclerosis (MS), and rheumatoid arthritis (RA)." (PMID 33160385, 2020). "Reduced total Cl levels in serum were found in one patient with anti-NMDAR encephalitis and one patient with anti-LGI1 encephalitis." (PMID 31178819, 2019). "We had two cases with anti-LGI1 encephalitis, that is, one with sleep disorder onset, and the other one with seizure onset, both of whom recovered after treatment." (PMID 31507515, 2019). "In the follow-up image of the anti-LGI1 encephalitis, caudate and putamen atrophy was observed, and this patient presented a higher frequency and duration of FBDS." (PMID 31139134, 2019). "Among them, anti-leucine rich glioma inactivated 1 (LGI1) encephalitis is a treatable etiology of AE." (PMID 30732585, 2019). "Our study indicated that patients with anti-LGI1 encephalitis are more prone to having autoimmune comorbidities than patients with anti-NMDAR encephalitis." (PMID 31736858, 2019). "Intriguingly, a spontaneous model of LGI1-Ab encephalitis has been observed in cats with feline complex partial seizures with orofacial involvement (FEPSO)." (PMID 32116982, 2019). "The proportion of patients with coexisting ADs was higher in those with anti–leucine-rich glioma-inactivated 1 (LGI1) encephalitis than in those with anti–N-methyl-d-aspartate receptor (NMDAR) encephalitis (13/111 vs. 16/307) (P = 0.021)." (PMID 31736858, 2019). "Children with anti-LGI1 or anti-CASPR2 encephalitis were rare and showed good response on immunotherapy." (PMID 31507515, 2019). "The proportion of patients with coexisting ADs was higher in those with anti-LGI1 encephalitis than in those with anti-NMDAR encephalitis (13/111 vs. 16/307) (P = 0.021)." (PMID 31736858, 2019). "Anti leucine-rich glioma inactivated 1 (LGI1) encephalitis is a rare autoimmune encephalitis (AE), characterized by acute or subacute cognitive impairment, faciobrachial dystonic seizures, psychiatric disturbances and hyponatremia." (PMID 30732585, 2019). "Postmortem analysis of three cases showed IgG and complement deposition associated with neuronal loss, consistent with the findings in the few available postmortem examinations from patients with LGI1-related encephalitis." (PMID 32116982, 2019). "Two patients had anti-LGI1 encephalitis, one of which was an 8-year-old boy with clinical manifestation mainly for insomnia." (PMID 31507515, 2019). "Anti‐LGI1 encephalitis most frequently occurred in middle‐aged males: of the nine anti‐LGI1‐positive patients, six were male, with median age of 51 years." (PMID 31650706, 2019). "Using immunohistochemistry, we verified the presence of neuronal-antibodies in CSF samples from NMDAR- and LGI1-encephalitis patients." (PMID 30944364, 2019). "We also found that patients with anti-LGI1 encephalitis were more prone to having autoimmune comorbidities than patients with anti-NMDAR encephalitis (P = 0.021)." (PMID 31736858, 2019). "Primary symptoms of LGI1 antibody encephalitis include memory impairments, seizures, FBDS, and mental and behavioral abnormalities." (PMID 29980179, 2018). "Based on some index cases with strikingly asymmetric FDG-PET uptake in LGI1-antibody encephalitis, we analyzed the FDG-PET, MRI, EEG, and clinical semiology lateralization in the patients and the LGI1 expression asymmetry in human brains." (PMID 30253786, 2018). "The group with AEDs withdrawal included 34 patients with anti-NMDAR encephalitis, 1 with anti-LGI1 encephalitis, 1 with anti-GABABR encephalitis, and 1 patient presented coexisting antibodies of anti-LGI1 and CASPR2." (PMID 30671012, 2018).